DKK3 (dickkopf Wnt signaling pathway inhibitor 3)
Diseases named in the same sentence as DKK3 in open-access papers (continued):
Sharing a sentence is not in itself a finding about the gene and the disease.
colon carcinoma (14 papers, 2013 to 2024). "For example, it suppressed Dickkopf 3 (DKK3) transcription to enhance migration and invasion in colon cancer." (PMID 36291656, 2022). "And the migration and invasion capacity were elevated after silencing DKK-3 expression by siRNA in colon cancer cells." (PMID 34124998, 2021). "Exosome-mediated transfer of miR-92a from colon cancer cells to endothelial cells leads to angiogenesis induction through downregulation of Dickkopf-3 (DKK3) and claudin-11." (PMID 31887997, 2019). "Reduced expression of TET1 is expected to result in direct deregulation of parathyroid target genes, as for example described in colon cancer for the DKK3 and DKK4 inhibitors of the WNT pathway." (PMID 26973719, 2016). "In serum samples from patients with colon cancer, DKK3 was detected in seven (22.6%) of 31, whereas ITIH5 was present in nine (29%) of 31 cases." (PMID 23320751, 2013). "The tumor suppressor DKK3 (RIG) induces apoptosis through mitochondrial pathways in human colon cancer and pro-apoptotic actions of PLAU in tumor cells have also been described." (PMID 23702334, 2013). "Additional specificity testing in 27 colon cancer samples revealed moderate methylation frequencies in all candidate markers with the exception of DKK3." (PMID 23320751, 2013). "Considering all control samples, including sera from patients with colon cancer, benign breast disease, and healthy controls, yielded a specificity of 93% (139 of 149) with combined DKK3 and ITIH5 methylation." (PMID 23320751, 2013). "Elevated expression of PRNP in homozygous mice was accompanied by increased expression of a set of genes that we previously identified as PrPC gene targets in colon cancer cells, namely App, Bace1, Dkk3, Pdgfc and Tgfb1, thus validating our model as a robust PRNP-overexpressing paradigm." (PMID 38589873, 2024). "DKK3 is an inflammatory suppressor and its mRNA level decreased after dextran sodium sulfate (DSS) induction in the free fatty acid receptor 2 (FFAR2)-deficient colon tumor mice." (PMID 36282328, 2022). "We first mined the TCGA-COAD data setto investigate the effect of high DKK3 and DKK4 expression on survivalprobability in a cohort of colon cancer patients." (PMID 36450103, 2023). "Furthermore, we demonstrated that the EVs secreted by colon cancer are enriched with miR-92a-3p and promote angiogenesis, as indicated by increased proliferation, motility, and tube formation in human umbilical vein endothelial cells (HUVECs) through the inhibition of Dickkopf-3 (Dkk-3) expression." (PMID 31500278, 2019).
glioblastoma (13 papers, 2014 to 2024). The most malignant astrocytic tumor (WHO grade IV). "We previously reported that expression of dickkopf-3 (DKK3), which is involved in the Wnt/β-catenin pathway, is significantly associated with prognosis in patients with glioblastoma multiforme (GBM)." (PMID 37149563, 2023). "Consistently, a machine learning approach proposed that high DKK-3 expression related to immunosuppression was associated with poor prognosis in glioblastoma." (PMID 38201279, 2023). "The analysis of transcriptomic data from 525 patients in The Cancer Genome Atlas database showed that DKK-3 correlates with immune suppression in glioblastoma." (PMID 38201279, 2023). "Our analysis of The Cancer Genome Atlas (TCGA) glioblastoma dataset revealed a positive correlation of REIC/Dkk3 and PDGFB or PECAM1 (CD31), suggesting the role of REIC/Dkk3 in angiogenesis." (PMID 36006934, 2022). "We showed a significant decreasing of Dkk-3 and claudin-5 in human glioblastoma cell lines, as well as in U-87 MG xenograft tumors and in glioblastoma human patient’s tissues, with an involvement of the apoptosis process." (PMID 30680070, 2018). "Modulation of this pathway through the expression of DKK3 could represent a new tailored therapeutic strategy in the treatment of glioblastoma." (PMID 38612910, 2024). "In glioblastoma multiforme, DKK3 affects both the canonical and non-canonical Wnt signaling pathways." (PMID 28969056, 2017). "In the present study we investigated the expression of Dkk-3, claudin-5, apoptosis markers and TLR-4 receptor protein levels in in vitro studies on U-138MG, A-172, LN-18 and LN-229 human glioblastoma cell lines, and in vivo study using TLR-4 KO mice and in glioblastoma human patient’s tissues." (PMID 30680070, 2018). "DKK3 has not been described in meningioma, but was reportedly downregulated in malignant glioma and its expression had anti-tumor effects in glioblastoma in vivo and in vitro (increased expression blocks the WNT signaling pathway, decreased expression activates it)." (PMID 29662628, 2018).
cardiac hypertrophy (12 papers, 2018 to 2025). "DKK-3 has additional roles in humans, relating to cartilage degradation, cardiac hypertrophy, artheroprotection, pulmonary ventilation and oxidative stress (Cell protection)." (PMID 38201279, 2023). "In cardiac hypertrophy, DKK3 attenuates cardiac fibrosis by promoting angiotensinogen II degradation." (PMID 37662558, 2023). "It was reported that DKK3 protects neurons against a variety of toxic insults via mediating vascular endothelial growth factor (VEGF), and DKK3 overexpression substantially alleviated cardiac hypertrophy and fibrosis." (PMID 35658977, 2022). "Consistent with above reports, DKK3 overexpression substantially alleviated cardiac hypertrophy and fibrosis." (PMID 32331523, 2020). "DKK3 presents cardioprotective effect in pathological cardiac hypertrophy via regulating the ASK1-JNK/p38 signaling pathway." (PMID 33041871, 2020). "Three genes linked to inhibition of cardiac hypertrophy were upregulate, viz., DKK3 (Dickkopf-3), FBXO32 (encoding E3 ligase, Fbxo32), and GADD45B, which blocks MKK7-induced JNK activation." (PMID 29556499, 2018). "Previous reports had already demonstrated that Dkk3 can protect against cardiac hypertrophy, and our group recently showed that Dkk3 is an atheroprotective cytokine." (PMID 29980568, 2018). "On the other hand, DKK3, a member of the dickkopf family, is a cardiac-enriched protein that plays an important role in heart development and presents cardioprotective functions as a negative regulator of pressure overload-induced cardiac hypertrophy." (PMID 35859587, 2022). "DKK3 overexpression substantially alleviated cardiac hypertrophy and fibrosis." (PMID 32331523, 2020). "Dickkopf-related protein 3 (DKK-3) is involved in heart development and cardiac hypertrophy protection and, in AF patients, elevated levels have been found in the atrial appendages and in circulation." (PMID 35859587, 2022).
renal fibrosis (12 papers, 2017 to 2025). A final common manifestation of a wide variety of chronic kidney diseases characterized by glomerulosclerosis and tubulointerstitial fibrosis. "Reducing Dkk3 protein level by mutation or antibody blockage can alleviate renal fibrosis and improve kidney functions." (PMID 29717119, 2018). "DKK3, a glycoprotein, has been shown to regulate Wnt/β-catenin signal transduction and promote the occurrence and development of renal fibrosis." (PMID 40406118, 2025). "Very similarly to PRO-C6, we observed that the urinary levels of DKK-3 increased with worse biopsy findings (e.g. in sclerotic class or extent of renal fibrosis more than 25%) in AAV." (PMID 37020541, 2023). "DKK3 therefore appears to be an important mediator of renal fibrosis and thus of deterioration in renal function." (PMID 35646976, 2022). "Potentially, elevated DKK3 urinary levels are indicative for active renal fibrosis, contributing to poorer outcome in CRS." (PMID 36166185, 2022). "They found that the low expression of DKK3 improves renal tubular atrophy, and reduces the accumulation of interstitial matrix in two mouse models of renal fibrosis by decreasing activation of Frizzled receptors." (PMID 33391006, 2020). "Studies have revealed that DKK3 promotes renal fibrosis by supporting the activation of Wnt signaling." (PMID 33391006, 2020). "A study showed that DKK3 modulates the local T cell response in renal fibrosis by changing the polarization of T cell, as shown via an increase in IFNγ-producing T cells." (PMID 33391006, 2020). "In this sense, specifically in the kidney, tubular epithelial cells are the predominant source of dickkopf 3 (DKK3), which acts as a profibrotic and immunosuppressive molecule that promotes renal fibrosis." (PMID 31608072, 2019). "Moreover, DKK-3 (Dickkopf-related protein 3) is known to play an important role in cardiac fibrosis and renal fibrosis." (PMID 35796776, 2023). "Similarly, high levels of DKK3 showed discriminatory power to identify patients with a higher degree of renal fibrosis with an AUC as high as 72%." (PMID 35683365, 2022). "However, in UUO rat models and adenine-induced nephropathy, DKK3 is a major driver of renal fibrosis, and the exact role of DKK3 on Wnt/β-catenin signaling remains poorly unclear." (PMID 34483931, 2021). "Moreover, DKK3 facilitates renal fibrosis by promoting EMT, impairing angiogenic competence, activating TGF-β, and modulating local T cell responses." (PMID 33391006, 2020). "Thus, interstitial fibroblasts may be more affected by DKK3 secreted by the epithelium, which is able to convert fibroblasts to myofibroblasts and result in renal fibrosis." (PMID 33391006, 2020). "The urinary DKK-3, EGF, PRO-C6 levels were also significantly related to the extent of renal fibrosis." (PMID 37020541, 2023). "Furthermore, only the urinary DKK-3, EGF and PRO-C6 levels were significantly related to the extent of renal fibrosis." (PMID 37020541, 2023). "Thus, DKK3 induces EMT and impairs angiogenic competence to give rise to renal fibrosis." (PMID 33391006, 2020). "In addition, DKK3 stimulated the expression of transforming growth factor-β (TGF-β), which is recognized as one of the most important factors leading to renal fibrosis." (PMID 33391006, 2020).
acute kidney injury (11 papers, 2018 to 2025). Sudden and sustained deterioration of the kidney function characterized by decreased glomerular filtration rate, increased serum creatinine or oliguria. "Furthermore, urinary DKK-3 is associated with acute kidney injury and subsequent chronic kidney dysfunction in patients undergoing cardiac surgery." (PMID 34207077, 2021). "Possibly, studies in specific disease cohorts, for example cohorts with patients diagnosed with renal failure, could provide more insight into DKK3 and its association with kidney disease." (PMID 33883651, 2021). "Moreover, preoperative DKK3 urine levels in patients undergoing cardiac surgery were predictive for post-operative acute kidney injury (AKI) and increased risk for long-term loss of kidney function." (PMID 33883651, 2021). "In particular, DKK3 is released by “stressed” TECs, which drives kidney fibrosis and is associated with a short-term risk of CKD progression and acute kidney injury." (PMID 38339031, 2024). "Urinary DKK-3 is a novel biomarker of acute kidney injury and CKD." (PMID 34207077, 2021). "In 471 patients, the DKK3 to creatinine ratios of >471 pg/mg were predictive of short-term acute kidney injury (AKI), persistent kidney impairment, and dialysis dependency." (PMID 37298105, 2023). "Dickkopf-3 (DKK3) has recently been discovered as a urinary biomarker for the prediction of acute kidney injury (AKI) after cardiac surgery." (PMID 33275197, 2021). "Beyond CKD, there is a first investigation on DKK3 in the context of acute kidney injury (AKI)." (PMID 33275197, 2021). "Advanced urinary injury markers for tubular (NGAL, DKK-3 and KIM-1) and glomerular damage (TIMP-2 and IGFBP-7) were recently introduced for monitoring acute kidney injury." (PMID 34640591, 2021). "In acute kidney injury (AKI), DKK3 is well studied and is seen as a predictor of a kidney failure." (PMID 38999343, 2024).
hepatocellular carcinoma (10 papers, 2009 to 2024). A malignant tumor that arises from hepatocytes. "Similar to other cancers, DKK3 expression was lower in the hepatocellular carcinoma cell lines (HepG2, SMMC-7721, and HuH7) than in normal liver cells (LO-2)." (PMID 27788486, 2016). "Also, a previous study has shown that GATA4 promoted oncogenesis through suppression of DKK3 expression in hepatoma cells." (PMID 33013201, 2020). "This GATA4/miR125b/DKK3 axis may be a major regulator of growth, migration, invasion, and survival in hepatoma cells, and is therefore a potential therapeutic target or biomarker for progression in HB patients." (PMID 27788486, 2016). "On the one hand, DKK3 has been shown to act as a tumor suppressor in many cancers and DKK3 overexpression has been investigated as a therapeutic target including a current phase I trial of adenovirus-vector-mediated DKK3 overexpression in liver metastases of hepatocellular carcinoma." (PMID 35796776, 2023). "Tumor suppression role of DKK3 protein was found in human cancers in ovary, cervix and colon; and expression of DKK4 protein was reduced in hepatocellular carcinoma tissue and could decrease the β-catenin protein levels." (PMID 27457487, 2016).
sarcopenia (10 papers, 2018 to 2026). Progressive decline in muscle mass due to aging which results in decreased functional capacity of muscles. "Another risk factor for sarcopenia is over‐expression of Dkk3, its over‐expression in young mice leads to progressive muscle mass loss." (PMID 37493006, 2023). "A direct causality between Dkk-3 expression and sarcopenia phenotype has been suggested as young mice with Dkk-3 overexpression mimic early sarcopenia phenotype while reducing Dkk-3 expression in aged mice partially offsets age-related muscle wasting." (PMID 33023021, 2020). "Moreover, secreted glycoprotein Dickkopf 3 (Dkk3) has been recently implicated in promoting aging sarcopenia by enhancing the nuclear import of β-catenin and promoting its interaction with FoxO3." (PMID 32635462, 2020). "Potential biomarkers for the diagnosis of sarcopenia concerning the Wnt pathway and in particular the presence of Dkk-3 and SREBP1 at the plasma level were also analyzed." (PMID 39997751, 2025). "The RNA‐seq results showed that NTs significantly downregulated the expression of sarcopenia‐related genes (Trim63, Dkk3 and Mt1)." (PMID 40745399, 2025). "Biomarkers in the Wnt signaling pathway which is correlated with sarcopenia were also reported in one study, including the Dkk-1, Dkk-3, and SREBP1 biomarkers." (PMID 37349622, 2023). "Together, these results reveal that reduction of Dkk3 level in old mice can improve both muscle fiber size and functions, suggesting Dkk3 to be a potential target to treat sarcopenia." (PMID 29717119, 2018). "Here we identified Dkk3 as the key secreted factor generated by muscles to induce sarcopenia and characterized the mechanism of Dkk3-dependent transcription activation of Fbxo32 and Trim63." (PMID 29717119, 2018). "Dkk3 is a marker for sarcopenia and its expression increases with age‐related muscle atrophy." (PMID 40745399, 2025). "Thus, it is possible that Dkk-3 activation has a greater contribution to relatively accelerated sarcopenia in the pulmonary TB compared to atrophy in more chronic diseases such as COPD and asthma." (PMID 33023021, 2020). "The serum Dkk3 concentration was significantly higher in old mice, suggesting that Dkk3 could be a marker for sarcopenia diagnosis." (PMID 29717119, 2018). "Here we identify a novel role for the secreted glycoprotein Dickkopf 3 (Dkk3) in sarcopenia." (PMID 29717119, 2018). "Knocking down Dkk3 in sarcopenia muscles could rescue not only the muscle fiber size but also the muscle contraction abilities." (PMID 29717119, 2018). "In summary, we showed that Dkk3 level in circulation could indicate the occurrence of sarcopenia." (PMID 29717119, 2018). "Dkk3 could serve as a diagnosis marker and therapeutic target for sarcopenia." (PMID 29717119, 2018). "Plasma levels of Dickkopf‐3 (Dkk‐3) and c‐terminal agrin fragment‐22 (CAF22) can suggest a sarcopenia phenotype in elderly individuals with respiratory diseases." (PMID 41582634, 2026). "Taken together, we have shown that the expressions of circulating Dkk-3, CAF22 and selected miRs have varying degrees of statistical relations with the indexes of sarcopenia and physical capacity in the elderly with respiratory diseases." (PMID 33023021, 2020). "We found a significant association of these biomarkers with HGS, ASMI and gait speed in COPD, asthma and pulmonary TB, which suggests that Dkk-3, CAF22 and selected miRs can be useful biomarkers of sarcopenia in respiratory diseases." (PMID 33023021, 2020). "Among the sarcopenia indexes, HGS showed the strongest correlation with plasma CAF22, miR-21 and miR-206 levels while ASMI showed the strongest correlation with Dkk-3 and miR-133 in respiratory diseases." (PMID 33023021, 2020). "Taken together, our data show that plasma levels of Dkk-3, CAF22 and selected miRs can be useful tools to assess accelerated sarcopenia phenotype in the elderly with respiratory diseases." (PMID 33023021, 2020).
sarcopenia (continued). "In this study, we investigated the direct correlation of circulating levels of Dkk-3, CAF22 and selected miRs with sarcopenia in respiratory diseases." (PMID 33023021, 2020). "We did not investigate the potential mechanism(s) by which Dkk-3 can contribute to sarcopenia in the elderly with respiratory diseases." (PMID 33023021, 2020). "DKK3, a myokine, regulates mitochondrial function and myotube structure via CKAP4 and may serve as a target for muscle atrophy prevention in conditions such as COPD-related sarcopenia or exercise-induced muscle wasting." (PMID 40870030, 2025). "However, a direct correlation of plasma Dkk-3 with muscle quality and/or quantity in sarcopenia has not been recognized before." (PMID 33023021, 2020). "In the context of sarcopenia, Dkk3 treatment does not affect canonical Wnt signaling." (PMID 29717119, 2018). "Thus, while we confirm and extend the usefulness of Dkk-3 as a biomarker of sarcopenia, it is possible that it might not accurately predict the accelerated sarcopenia phenotype in all age-related systemic diseases." (PMID 33023021, 2020).
kidney damage (9 papers, 2021 to 2025). "After kidney damage, DKK3 is expressed in the tubular epithelial cells and causes a profibrotic T-cell response." (PMID 35646976, 2022). "The urinary DKK3 (uDKK3), assessed through the DKK3-to-creatinine ratio (uDKK3/uCr), has been thoroughly investigated in multiple nephropathies, particularly CIN, which frequently occurs after exposure to iodinated contrast media during CA and PCI." (PMID 40243457, 2025). "values were found in G3 and G5 suggest that urinary Dkk3 may indicate ongoing renal injury and can reflect the advancement of kidney damage." (PMID 37510820, 2023). "Increased levels of DKK3 detected at baseline were also observed in those patients who experienced a worsening of kidney function over the years, further suggesting a specific role in kidney damage progression." (PMID 35683365, 2022). "This suggests that in subjects in which kidney damage is close to absent, blood plasma DKK3 can add to CKD risk prediction." (PMID 33883651, 2021). "Among the 9,628 participants with available urinary kidney damage biomarker data in Uppsala (n = 4,717) and Malmö (n = 4,911), KIM-1 and EGF were only available in Uppsala, whereas osteopontin and DKK-3 were measured both in Uppsala and Malmö." (PMID 39587192, 2024). "DKK3, as a marker of tubular damage, is described in this review and has been shown to have implications as a biomarker for CKD and kidney damage in the context of diabetes, after cardiac surgery, and in contrast-media-associated kidney injury." (PMID 37298105, 2023). "This is further supported by the fact that in CKD patients urinary DKK3 levels strongly correlate with UAE14, whilst in this study only a minor correlation between plasma DKK3 and UAE was observed, indicating that urinary DKK3, but not plasma DKK3, is associated with kidney damage." (PMID 33883651, 2021).